ENSG00000259753 (novel protein)
Gene: Protein-coding gene on chromosome 17 (47,253,897 to 47,344,292, forward strand). Ensembl gene ENSG00000259753.
Genetic constraint (gnomAD): Missense variants: 809 observed, 1,008.7 expected, observed/expected ratio (o/e) 0.8, 90% interval 0.76 to 0.85. Synonymous variants: 335 observed, 383.02 expected, observed/expected ratio (o/e) 0.87, 90% interval 0.8 to 0.96.